RNU6-888P (RNA, U6 small nuclear 888, pseudogene)
Gene: Small nuclear RNA gene on chromosome 5 (138,123,011 to 138,123,111, reverse strand). Ensembl gene ENSG00000199880.
Homologues: Orthologues: chimpanzee U6 (98% identical), macaque U6 (92% identical), guinea pig U6 (62% identical). Paralogues in human: RNU6-1122P (84% identical), RNU6-41P (84% identical), RNU6-15P (83% identical), RNU6-166P (83% identical), RNU6-44P (83% identical), RNU6-820P (83% identical), RNU6-1019P (82% identical), RNU6-1060P (82% identical), RNU6-1266P (82% identical), RNU6-12P (82% identical), RNU6-13P (82% identical), RNU6-25P (82% identical), and 1285 more.